IL13 (interleukin 13)
Diseases named in the same sentence as IL13 in open-access papers (continued):
Sharing a sentence is not in itself a finding about the gene and the disease.
food allergy (continued). "While IL-17A signaling has been implicated in both allergic inflammation and PSO, there was less enrichment of genes involved in the proallergic IL-4 and IL-13 responses, despite the fact that patients with SAM syndrome often develop food allergies and have elevated levels of IgE." (PMID 34905516, 2022). "We first examined the gene expressions of IL-4, IL-5, and IL-13 in water-treated mice with or without food allergy." (PMID 36501013, 2022). "This is the first study that aims to detect the expression of Th2 cytokines (IL-4, IL-5, IL-10, and IL-13) in infants with non-IgE food allergy and to compare it to peer healthy subjects." (PMID 35458127, 2022). "Our data revealed that values of IL-4 and IL-13 are higher in infants with non-IgE-mediated food allergies, whereas IL-5 and IL-10 are lower, as observed in IgE-mediated food allergies." (PMID 35458127, 2022). "OVA-sensitized mice were protected from food allergy anaphylactic death by 60% and observed with significantly suppression of OVA-specific IgE,IL-17, TH2 cytokines (IL-4, IL-5, IL-10, IL-13) and TH1 cytokines (IFN-γ and IL-12) with the treatment of 25 mg/kg of extract." (PMID 31275149, 2019). "Importantly, serum IL-4, but not IL-13, concentrations were significantly higher in patients with food allergy and S. aureus colonization than in those with S. aureus colonization but no food allergy." (PMID 41005294, 2025). "Although increased production of IgE and Th2 cytokines (IL-4, IL-5 and IL-13) are considered common markers of food allergy, absence of IgE or increased levels of Th1 cytokines (IL-2, IFN-γ and TNF-α) have also been observed in several instances of food allergy, mainly in response to cow's milk." (PMID 21211037, 2011). "The repurpose of antibodies that improve severe atopic dermatitis symptoms in patients with and without food allergies may warrant investigation for food allergy management due to the similarities in pathogenesis, including the IL-13 antagonists tralokinumab and lebrikizumab." (PMID 40004029, 2025).
depression (46 papers, 2016 to 2025). "One of the selection criteria for the particular cytokine panel investigated, which included IL-13, was the previously published association between allergies and depression or even suicide." (PMID 36614020, 2022). "Indeed, higher IL-13 levels are associated with more severe depression and a higher number of suicide attempts, and elevated levels of IL-2, TNF-a, and IL-8 are associated with depressive symptoms in clinical studies." (PMID 39297528, 2024). "Our result that the lower level of IL-13 was associated with depression might be related to the synergy of IL-4 reduction, with the need for further research to prove it." (PMID 38426163, 2024). "In our study, the authors found the levels of IL-4, IL-13, eotaxin, and IP-10 were significantly lower in the depression of TA patients." (PMID 38426163, 2024). "The authors found that depression was correlated with lower levels of IL-4, IL-13, eotaxin, and IP-10, suggesting the abnormal immune responses contributing to the evolution of depression in TA." (PMID 38426163, 2024). "Increased levels of cytokines such as IL-6, IL-10, IL-12, IL-13, and IL-17 were found in individuals with depression." (PMID 37240864, 2023). "Depression was associated with a lower IFN-γ level and an elevated IL13 level; the functions of IL13 have similarities with the role of IL5." (PMID 36009493, 2022). "TNF-α, IFN-γ, IL-5, IL-12 and IL-13 were also related to the severity of depressive symptoms, as well as the somatic–affective and cognitive dimensions of depression." (PMID 35407580, 2022). "Patients with depression showed increased levels of IL-8, IL-10, IL-12, and IL-13, whereas IL-6 and TNF-α showed mixed results between studies." (PMID 33578686, 2021). "Based on the univariate analysis of the GLM, we found significant differences in the years of education, cytokines (IL-1β, IL-2, IL-6, IL-12p70, IL-17A, IFNγ, TNFα, IL-10, and IL-13), and depression severity (indicated by the PHQ) among the groups." (PMID 32703187, 2020). "First, we found that the baseline levels of IL-10, IL-12p70, IL-13, IL-17A, IL-1β, IL-2, IL-23, IL-5, IL-6, IL-7, and MIP-1β were associated with depression symptoms." (PMID 32699226, 2020). "TNF-α, IFN-γ, IL-5, IL-12, and IL-13 were further related to the severity of depressive symptoms, as well as the somatic-affective and the cognitive dimensions of depression." (PMID 30524320, 2018). "In addition, a post-mortem study revealed that the expression of the anti-inflammatory cytokines IL-13 and IL-4 was increased in the orbitofrontal cortices of female and male suicide victims, who had been diagnosed with depression." (PMID 33672958, 2021). "Although IL13RA2 is known to be implicated mainly in cancer, its ligand IL-13 regulates inflammation, so this gene could also play a part in increased inflammation seen in patients with depression." (PMID 33193575, 2020). "In the post C/T group, four factors were independent predictors of SFT: IQ and anxiety had significantly positive associations with SFT, while depression and log-IL-13 levels had significantly negative associations with SFT, i.e., the higher the log IL13, the poorer the performance on SFT." (PMID 34073990, 2021). "In our review, we noticed that IL-13 decreased with the administration of the SSRI escitalopram (one study, moderate depression)." (PMID 40573262, 2025). "After 24 weeks of HFHSD exposure, male mice showed a general depression in the expression of cytokines, with prominent reduction of TNF-α, IL-6 and IL-13, but increased TGF-β, while female mice showed over-expression of IFN-γ and IL-18." (PMID 39302596, 2024). "In particular, tumor necrosis factor alpha (TNFα), interleukin-2 (IL-2), interleukin-6 (IL-6), interleukin-13 (IL-13), interleukin-18 (IL-18), C-reactive protein (CRP), chemokine-2 (CCL2), and chemokine-11 (CCL11) are elevated in depression based on multiple meta-analyses." (PMID 32351416, 2020).
depression (continued). "According to the current literature, it seems that peripheral levels of interleukin (IL)-6, IL-10, IL-12, IL-13, and tumor necrosis factor (TNF)-α are elevated and that interferon (IFN)-γ levels are lower in patients with depression compared to healthy controls." (PMID 30792669, 2019). "Similar to the findings in CP/CPPS patients, elevated levels of IL-1α, IL-1β, IL-4, IL-13, and TNF-α were observed in CP/CPPS rat prostates, and these elevated cytokine levels showed a positive trend in their correlation with anxiety, depression, and memory impairment." (PMID 27334333, 2016). "However, IL-13 was proven only one-tenth of the inhibiting effect of IL-4 in RA, without a direct correlation with depression." (PMID 38426163, 2024). "Up to now, we have not found other studies reporting disturbances in IL-13 in MDD adolescents and thus its role in depression remains unclear." (PMID 30662368, 2018).
Granuloma (45 papers, 2009 to 2025). A compact, organized collection of mature mononuclear phagocytes, which may be but is not necessarily accompanied by accessory features such as necrosis. "While these studies have implicated type 2 immune responses driven by IL-4 and IL-13 in granuloma pathology, there are still a number of outstanding questions about how, when and where these cytokines are produced." (PMID 35320930, 2022). "Thereafter IL-13, using AA macrophages and fibroblasts, causes granulomas to decrease in size and become fibrotic." (PMID 34281269, 2021). "IL-4 and IL-13 determine the inflammatory phenotype of egg-induced granulomas and IL-13 causes fibrosis." (PMID 29743881, 2018). "In these mice, the IL-13-mediated increased susceptibility, human-like pathology of collagen deposition around centrally necrotizing granulomas, and alternative macrophage activation were abolished." (PMID 26977119, 2016). "Most importantly, the present study showed IL-13 over-expression to cause recrudescent Mtb replication and centrally necrotizing granulomas in experimental TB, strongly resembling the pathology of human TB." (PMID 24979482, 2014). "Notably, the expression level of interleukin 13, an inflammatory factor closely related to the formation of granuloma caused by S. japonicum, was significantly reduced." (PMID 35943970, 2022). "Consistent with the higher RVSP, the size of peri-vascular granulomas was modestly larger, although the concentrations of IL-4 and IL-13 were unchanged in S. mansoni-exposed mice." (PMID 41055564, 2025). "Cytokines such as IL-1β, IL-4 IL-5, IL-6, IL-13, TNF-α, MCP-1, and TSLP induce allergy-related inflammation, which causes tissue fibrosis, granuloma formation, and leukocyte infiltration." (PMID 36235405, 2022). "The choice to specifically study MD-macrophages in these patients was supported by recent works showing that in vitro models of granuloma using PBMCs can mimic sarcoidosis events such as phagosome-regulated mTOR or IL-13 signaling." (PMID 34456926, 2021). "In order to correlate the extent of Mtb-induced necrosis to inflammasome activation in vivo, we exploited transgenic IL-13-overexpressing mice, which show human-like lesions and necrotizing granuloma in the lungs upon Mtb infection." (PMID 34718331, 2021). "The role of individual Th2 cytokines in granuloma formation and fibrosis have been shown to be different in that IL‐4 or IL‐13 can both generate granuloma formation, while IL‐13 alone is the dominant pro‐fibrotic cytokine in this disease." (PMID 32692855, 2021). "Between 10 and 60 days, the increased IL-13 resulted in a M2a macrophage phenotype when granulomas were resolving in MWCNT-instilled Mmp12 KO mice." (PMID 34681679, 2021). "Intriguingly, IL-13 has been reported to act as an inducer of fusion-driven MNGC formation and contributes to macrophage polarization in sarcoidosis-associated granuloma formation in vitro." (PMID 33050608, 2020). "Classically, the granuloma evolution is related to a Th2 cytokine profile (i.e., IL-4, IL-5, and IL-13) and lower IFN-γ expression." (PMID 31019973, 2019). "Type-2 cytokines, such as IL-5, IL-4, and IL-13, are responsible for the recruitment and activation of immune cells involved in granuloma formation, whereas IL-10 has been related to the granuloma modulation." (PMID 31886307, 2019). "In the present study we detected IPSE/alpha-1, recruited basophils, and IL-13 in egg-induced granulomas attached to the colon of co-infected mice by immunohistological staining." (PMID 30487793, 2018). "This is in line with another study that has established the fact that IL-13 exhibits chemotactic activity for human eosinophils; therefore, schistosome granulomas are rich in eosinophils." (PMID 27648452, 2016).
Granuloma (continued). "In contrast, in experimental TB we have recently shown that overexpression of IL-13 in Mtb-infected mice results in recrudescent mycobacterial growth accompanied by centrally necrotizing granulomas strongly resembling pathology of human TB." (PMID 26977119, 2016). "In the present study, however, over-expression of IL-13 in fact led to recrudescent Mtb growth accompanied by centrally necrotizing granulomas." (PMID 24979482, 2014). "Administration of cystamine, an inhibitor of tTG, abrogated the increase in both tTG and IL-13 in infected mice and ameliorated liver fibrogenesis and granuloma development." (PMID 25110399, 2014). "Five weeks after Sj infection, granuloma and fibrosis development in the liver coincided with an increase in IL-13 and tTG in the liver and the upregulation of serum IL-13 in infected mice." (PMID 25110399, 2014). "In the schistosome pulmonary granuloma model, studies conducted with IL-4−/−, IL-13−/−, and IL-4−/−/IL-13−/− double knockout mice demonstrated that egg-induced granuloma formation is dependent on both IL-4 and IL-13." (PMID 19381262, 2009). "Studies with the helminth egg-induced granuloma model showed that Retnla expression was strongly dependent on the Th2 cytokines IL-4 and IL-13 and negatively regulated by IFN-γ." (PMID 19381262, 2009). "Inhibition of IL-4 and IL-13, key players in the differentiation and activation of Th2 cells, may shift the Th1/Th2- ratio toward an excessive Th1-mediated response, granuloma formation, and drug-induced (neuro)sarcoidosis reaction." (PMID 35795795, 2022). "Even though, Mmp12 KO mice instilled with MWCNT are intrinsically an M2 phenotype, our data suggest that the necessary M2c to M2a shift for granuloma resolution might be induced by IL-13." (PMID 34681679, 2021). "Together, we here introduce an experimental TB model that displays many features of centrally necrotizing granulomas in human post-primary TB and demonstrate that IL-13/IL-4Rα-dependent mechanisms leading to arginase-1 expression are involved in TB-associated tissue pathology." (PMID 24979482, 2014). "Indeed, the depletion of either cytokine alone reduced granulomatous inflammation by half, while the simultaneous depletion of both IL-4 and IL-13 nearly ablated granuloma development." (PMID 19381262, 2009). "This spatial model accounted for granulomas as evolving regions over time and incorporated variables such as the density of macrophages, Treg, Th1, and Th17 cells, as well as concentrations of IL-2, IL-10, IL-12, IL-13, IFN-γ, TNF-α, TGF-β, GM-CSF, and CCL20, along with fluid velocity." (PMID 39996765, 2025). "considers the progression of sarcoidosis in terms of a granuloma radius represented as a conglomerate of Mφ, Th1, Treg and Th17 cells, which affect each other through a network of cytokines and chemokines (IL-2, IL-10, IL-12, IL-13, chemokine ligand 20, IFN-γ, TNF-α and TGF-β)." (PMID 38550585, 2024). "It is also conceivable that IL-4/IL-13 production in the perivascular adventitial space—likely more relevant to vascular remodeling—may be masked by whole-lung assessments such as IL-4/IL-13 levels in whole lung lysates, and analysis of peri-egg granulomas." (PMID 35417453, 2022). "In the present study, significant IL-13 levels were detected in non-HIV patients with histoplasmosis and pneumocystosis, which could be related to IL-13 role in granuloma development, in contrast to the low levels reported in lung granulomas of H. capsulatum-infected mice." (PMID 34829225, 2021). "While schistosome eggs have also been characterised to induce IL-13 and TGF-β to lead to granuloma development, it is interesting that we observed a resolution of intestinal fibrosis in SMDSS mice." (PMID 40332187, 2025). "Blockade of IL-4 in PPD-bead granuloma models in wild-type mice results in augmented IFN-γ production, and blockade of both IL-4 and IL-13 augments granuloma size." (PMID 21655295, 2011).
Granuloma (continued). "Additionally, we observed an enhanced expression of IL13Rα1, Jak3, and STAT6 in macrophages within CS granulomas and the increased phosphorylation of Jak3 and STAT6 are indicative of an activation of anti-inflammatory IL4/IL13 signaling pathways." (PMID 40521183, 2025). "In contrast to non-transgenic C57BL/6 littermates, IL-13 overexpressing animals infected with Mtb formed organized necrotic granulomas that closely resembled human disease, suggesting that type 2 pathways contributed to necrotic granuloma formation." (PMID 35320930, 2022). "Liver cells around granulomas also showed strong expression of TGF-β1 and IL-13." (PMID 25590646, 2015). "Interestingly, they observed an IL-13-dependent overexpression of STAT6, reflecting a Th2-mediated inflammatory response that drives M2 macrophage polarization, as found in tissue samples of sarcoidosis granuloma." (PMID 39996765, 2025). "Because IL-4 and IL-13 are hardly expressed after M. tuberculosis infection in wild-type mice, which do not form centrally necrotizing granulomas, we hypothesized that an increase in IL-13 expression leads to the development of necrotic lesions." (PMID 34871095, 2022). "Since no functional connection between IL-4/IL-13 and the development of granuloma necrosis in TB patients was available, we previously analyzed the association of gene variants in the common receptor subunit IL4RA and disease severity in a large patient TB cohort." (PMID 34871095, 2022). "We demonstrated reduced serum levels of both TH2 cytokines (IL-13 and -4) accompanied by reduced numbers of CD3+ and Ki-67+ cells in granulomas of the norUDCA (but not UDCA) group." (PMID 25463533, 2015).